CUL4A (cullin 4A)
Diseases named in the same sentence as CUL4A in open-access papers (continued):
Sharing a sentence is not in itself a finding about the gene and the disease.
breast carcinoma (continued). "In addition to reported upregulation in breast carcinomas, high level of CUL4A expression was also found in squamous cell carcinoma of the esophagus, Adrenocortical carcinoma, childhood medulloblastoma, hepatocellular carcinomas, malignant pleural mesothelioma and prostate cancer." (PMID 25413624, 2014). "This genomic aberration could facilitate the tumor progression through the overexpression of driver/target genes such as TFDP1 and CUL4A, which are overexpressed not only in Amp13q34 tumors, but also in other breast cancer samples characterized by a high cell proliferation and aggressiveness." (PMID 19995430, 2009). "It has been reported that CUL1, CUL2, CUL4A and CUL5 are efficiently deNEDDylated by MLN4924 in MCF breast cancer cells." (PMID 35880551, 2022). "Youden index analysis also showed that five proteins including S100A9, SRSF6, THBS1, CUL4A, and CANX can accurately diagnose breast cancer patients at the metastatic and primary stages from healthy individuals." (PMID 32793473, 2020). "The identified PBMC biomarkers (TMSB4X, HSPA4, S100A9, SRSF6, THBS1, CUL4A, and CANX) were significantly upregulated in the breast cancer patients at the metastatic stage compared to both the primary stage and healthy individuals (p < 0.001)." (PMID 32793473, 2020). "Moreover, an increase of de novo DNA methylation activity of DNMT3B following its interaction with NEDDylated CUL4A (CUL4A-NEDD8) could be involved in local DNA hypermethylation and was reported in tissues (e.g., breast cancer (BC) and hepatoma) overexpressing CUL4A." (PMID 29449903, 2018). "Another study suggested a synergistic effect between CUL4A overexpression and the activation of the H-RAS (v-Ha-ras Harvey rat sarcoma viral oncogene) pathway in the tumorigenesis of basal-like breast cancers." (PMID 28576144, 2017). "These genes include: transcription factor Dp-1 (TFDP1), cullin 4A (CUL4A), and cell division cycle 16 (CDC16) identified in hepatocellular carcinoma (HCC), breast cancer, and lung cancer; and insulin receptor substrate 2 (IRS2) present in colorectal cancer." (PMID 26684807, 2015). "CUL4A, which has the highest homolog with CUL4B, is overexpressed in primary breast cancers and hepatocellular carcinomas, and overexpression of CUL4A is associated with poor outcome in node-negative breast cancer." (PMID 25945838, 2015). "Our results suggest a synergistic effect between CUL4A high levels and the activation of the RAS pathway in the tumorigenesis of basal-like breast cancer tumors." (PMID 24870930, 2014). "Therefore, we presume that CUL4A may regulate MDR in breast cancer through modulation of ERK1/2." (PMID 24368600, 2013). "Recent research showed that CUL4A has a relationship with MDR in prostate cancer too, but the relationship between CUL4A and MDR and related mechanisms in breast cancer are still unclear." (PMID 24368600, 2013). "In addition, following 6 h treatment with MLN4924, CUL1, CUL2, CUL4A and CUL5 are efficiently deNEDDylated in MCF breast cancer cells." (PMID 35880551, 2022). "CUL4A degrades DBB, through ubiquitin-proteasome pathway to damage the activity of DNA, weakens the ability of DBB to recognize and repair damaged DNA in tumor cells, and finally advances the development of breast cancer." (PMID 33461174, 2021). "Finally, in silico analysis confirmed that a gene set consisting of S100A9, SRSF6, THBS1, CUL4A, and CANX were found to provide an insight for the identification of metastasis in breast cancer patients." (PMID 32793473, 2020). "Taken together, these data suggest that CUL4A is a critical component in chemoresistance, and H19, CUL4A, ABCB1 and ABCC4 work coordinately to display the action on modulation of multidrug resistance in breast cancer cells." (PMID 29190892, 2017). "The survival of breast cancer patients without chemotherapy was not related to tumor CUL4A expression." (PMID 29190892, 2017).
breast carcinoma (continued). "In addition, Cul4A and ERK1/2 participate in multidrug resistance in breast cancer through regulation of multidrug resistance 1 gene (MDR1)/P‐gp expression." (PMID 26969027, 2016). "And a recent study illustrated that CUL4A promoted H3K4me3 at the promoter of ZEB1 and then led to transcriptional upregulation of ZEB1 expression in breast cancer cells, and knockdown of ZEB1 blocked CUL4A-induced cell proliferation, EMT, tumorigenesis, and metastasis." (PMID 26460955, 2015). "Since basal-like breast cancers are characterized by lack of effective targeted therapy and poor clinical outcome, the elucidation of the specific role of CUL4A in the carcinogenic process of this tumor subtype is of major interest." (PMID 24870930, 2014). "We examined the expression of CUL4A in 11 human breast cancer cell lines and two non-transformed human mammary epithelial cell lines by quantitative PCR (qPCR) and Western blot (WB)." (PMID 24870930, 2014). "To directly assess the contribution of endogenous CUL4A overexpression on the transformed phenotype of human breast cancer cells, we examined the effects of knocking down CUL4A in the HCC1937 and MDAMB157 breast cancer cell lines where CUL4A is amplified and/or overexpressed." (PMID 24870930, 2014). "Breast cancer patients with strong expression of CUL4 show shorter overall and disease-free survival which has led to the proposal that CUL4A might confer an aggressive behavior in this malignancy." (PMID 24870930, 2014). "In addition, they described amplification of CUL4A (25.7%), LAMP1 (13.5%), TFDP1 (31.1%), and GAS6 (13.5%) by DNA qRT-PCR on a set of 74 human breast carcinomas." (PMID 19995430, 2009). "Finally, a gene set consisting of S100A9, SRSF6, THBS1, CUL4A, and CANX were introduced as potential candidate genes helpful in distinguishing metastatic from non-metastatic breast cancer patients." (PMID 32793473, 2020).
hepatocellular carcinoma (24 papers, 2007 to 2025). A malignant tumor that arises from hepatocytes. "Taken together, the findings of the present study revealed a new mechanism by which LINC01468-mediated lipogenesis promotes hepatocellular carcinoma progression through the CUL4A-linked degradation of SHIP2." (PMID 36344496, 2022). "DLX6-AS1 inhibits ANXA10 expression through ubiquitination-mediated degradation to accelerate hepatocellular carcinoma development, which can be attributed to the regulation on miR-513c/Cul4A axis." (PMID 36660176, 2023). "lncRNA uc.134 inhibits the aggressiveness of hepatocellular carcinoma via suppressing CUL4A-mediated ubiquitination of LATS1." (PMID 37013491, 2023). "A study discovered that a new lncRNA called uc.134 slows the growth of hepatocellular cancer by preventing LATS1 from being ubiquitinated by CUL4A." (PMID 36267408, 2022). "For example, LncRNAuc.134 inhibits the progression of hepatocellular carcinoma by inhibiting CUL4A-mediated LATS1 ubiquitination." (PMID 35860629, 2022). "Amplification and overexpression of CUL4A were reported in different tumor types (e.g., breast and prostate cancer, hepatocellular carcinoma)." (PMID 34202213, 2021). "For instance, lncRNA uc.134 inhibits CUL4A-mediated ubiquitination of LATS1 to hinder hepatocellular carcinoma progression." (PMID 33568633, 2021). "Uc.134, a novel lncRNA, elevates YAPS127 phosphorylation and represses LATS1 ubiquitination mediated by CUL4A to inhibit the progression of hepatocellular carcinoma." (PMID 34401209, 2021). "For example, one study indicated that uc.134 represses hepatocellular carcinoma development by inhibiting CUL4A-mediated ubiquitination of LATS1 and that uc.416 inhibits miR-153 and promotes epithelial-to-mesenchymal transition in renal cell carcinoma." (PMID 32303004, 2020). "Our study identifies that a novel lncRNA, uc.134, represses hepatocellular carcinoma progression by inhibiting the CUL4A-mediated ubiquitination of LATS1 and increasing YAPS127 phosphorylation." (PMID 28420424, 2017). "It was reported that the CUL4A gene showed amplification in some human primary hepatocellular carcinomas (HCC)." (PMID 26593394, 2015). "Since CUL4A amplification has been noted in breast and hepatocellular cancer, it will be interesting to determine if CUL4A/4B gene dosage alters tumor progression in vivo." (PMID 17280619, 2007). "For instance, CUL4A mediates the ubiquitination of LATS1 to regulate YAP activity in hepatocellular carcinoma, AGK inhibits the activation of the Hippo pathway proteins in GC38 and CD44 functions upstream of the Hippo signalling pathway and attenuates its activation in glioblastoma." (PMID 37555915, 2023). "Certainly, a notable proportion of lncRNAs have also been found to regulate protein expression through ubiquitination: lncRNA uc.134 could repress hepatocellular carcinoma progression by inhibiting the CUL4A-mediated ubiquitination of LATS1 and increasing YAPS127 phosphorylation." (PMID 32351584, 2020). "Studies utilizing comparative genomic hybridization (CGH) found recurrent 13q14 amplification, of which CUL4A may be a target, in various types of tumors, including esophageal squamous cell carcinoma, adrenocortical carcinoma, hepatocellular carcinoma, and childhood medulloblastoma." (PMID 28576144, 2017).
lung carcinoma (23 papers, 2014 to 2025). "On the other hand, the knockdown of Cul4A is associated with the decreased invasion and metastasis of lung cancer cells and tumors." (PMID 31052599, 2019). "Cul4A overexpression has been observed in 50% to 87.2% of lung cancer tissues, and it has been associated with poor prognosis of lung cancer patients in previous studies." (PMID 31052599, 2019). "The association of Cul4A with metastasis and invasion of lung cancer cells was explored both in vitro and in vivo." (PMID 31052599, 2019). "In this study, the association of Cul4A expression with clinical prognosis was studied in lung cancer patients after surgical resection." (PMID 31052599, 2019). "Depletion of cullin 1 also leads to increased expression of MTSS1, while the knockdown of Cul4A is associated with the growth inhibition of lung cancer cells." (PMID 31052599, 2019). "In this study, we observed that the upregulated Cul4A is associated with poor prognosis in NSCLC lung cancer patients after surgery." (PMID 31052599, 2019). "In H1975 lung cancer cells, overexpression of Cul4A was also associated with increased anchorage‐dependent colony formation and decreased chemosensitivity to gemcitabine." (PMID 26969027, 2016). "In summary, our study showed that Cul4A plays important roles in cell growth and survival in lung cancer cells and knockdown of Cul4A is associated with increased chemosensitivity to gemcitabine." (PMID 26969027, 2016). "Our results showed that knockdown of Cul4A is associated with growth inhibition in lung cancer cells." (PMID 26969027, 2016). "Changes in drug susceptibility to common chemotherapy reagents after Cul4A knockdown by shRNA in lung cancer cells were also evaluated in our study." (PMID 26969027, 2016). "The expression of P21 and XPC is negatively associated with CUL4A in lung cancer." (PMID 32587774, 2020). "However, the effect of Cul4A on lung cancer cells metastasis and the association of metastasis suppressors with Cul4A is rarely explored in lung cancer cells." (PMID 31052599, 2019). "Knockdown of Cul4A is associated with increased chemosensitivity to cisplatin in lung cancer cells." (PMID 26969027, 2016). "For instance, overexpression of ubiquitin ligases, such as Cullin-RING ubiquitin ligase 4 A (CUL4A), is common in cigarette smoke-related lung cancer, and inversely correlates to XPC expression." (PMID 35530314, 2022). "Consistently, a previous study has shown that KDM4C can increase cell migration and invasion via CUL4A in lung cancer." (PMID 32908544, 2020). "A previous report showed that ANXA10, regulated by Cullin 4A, modulates invasion and metastasis of lung cancer." (PMID 33177783, 2020). "Remarkably, no obvious change in the ANXA10 mRNA levels was observed in the Cul4A shRNA transfected groups of lung cancer cells compared to the cells transfected with the empty vector." (PMID 31052599, 2019). "The knockdown of Cul4A is associated with the increased expression of ANXA10, a tumor suppressor protein, in lung cancer cells." (PMID 31052599, 2019). "Cul4A also plays important roles in lung cancer invasion and metastasis partially through ubiquitin-mediated protein degradation of ANXA10 in lung cancer cells." (PMID 31052599, 2019). "The knockdown of Cul4A was associated with the upregulation of ANXA10, and the forced expression of Cul4A was associated with the downregulation of ANXA10 in lung cancer cells." (PMID 31052599, 2019). "Our findings suggest that Cul4A is a prognostic marker in NSCLC patients after surgery of lung cancer." (PMID 31052599, 2019). "Further studies showed that the knockdown of Cul4A inhibited the invasion and metastasis of lung cancer cells, which was reversed by the further knockdown of ANXA10." (PMID 31052599, 2019). "We observed that the knockdown of Cul4A significantly repressed metastasis and invasion of lung cancer cells." (PMID 31052599, 2019).
lung carcinoma (continued). "Cul4A is overexpressed in several cancers, including breast, mesothelioma, lung cancer, and liver cancers." (PMID 31052599, 2019). "Our results add ANXA10 to the repertoire of tumor suppressor proteins that are inhibited by Cul4A in cancer, and thus, it suggests Cul4A as a potential drug target for the development of novel therapy for lung cancer in the future." (PMID 31052599, 2019). "An increased expression of ANXA10 was also observed in the Cul4A knockdown H460 and A549 cells compared to the empty virus transfected lung cancer cells." (PMID 31052599, 2019). "In transgenic mouse models, the development of lung cancer after conditional overexpression of Cul4A has also been observed." (PMID 31052599, 2019). "Our findings suggest that Cul4A is a prognostic marker in NSCLC patients, and Cul4A plays important roles in lung cancer invasion and metastasis through the regulation of the ANXA10 tumor suppressor." (PMID 31052599, 2019). "A nude mouse tail vein injection metastasis model was established in our study, which showed a decreased metastatic potential in Cul4A knockdown lung cancer cells." (PMID 31052599, 2019). "Effects of Cul4A knockdown on metastasis and invasion of Cul4A shRNA transfected H460 and A549 stable lung cancer cells were evaluated using cell migration and invasion assays." (PMID 31052599, 2019). "In conclusion, our results showed that Cul4A is important in lung cancer cell invasion and metastasis through the inhibition of ANXA10, a tumor suppressor." (PMID 31052599, 2019). "The mechanism of lung cancer invasion and metastasis regulated by Cul4A is complex, and further studies regarding Cul4A and other metastasis suppressors are still warranted in the future." (PMID 31052599, 2019). "We observed an increase in the ANXA10 protein level in Cul4A knockdown lung cancer cells using western blotting." (PMID 31052599, 2019). "Our previous study found that CUL4A is overexpressed in non-small cell lung cancer tissues and can promote the proliferation of lung cancer cells." (PMID 31060565, 2019). "Similar to the results observed with transient siRNA transfection, H460 and A549 lung cancer cells were stably transfected with Cul4A shRNA using retroviral transduction, which resulted in the knockdown of Cul4A, and showed increased ANXA10 protein levels." (PMID 31052599, 2019). "In our previous unpublished study, the upregulation of ANXA10 was observed in Cul4A knockdown lung cancer cells." (PMID 31052599, 2019). "Protein degradation assay was used to evaluate the stability of ANXA10 protein in Cul4A knockdown and overexpressed H460 lung cancer cells." (PMID 31052599, 2019). "After treated with cycloheximide for the indicated periods, protein degradation was dramatically increased in the Cul4A overexpressed lung cancer cells, while Cul4A knockdown lung cancer cells showed a marked reduction in protein degradation." (PMID 31052599, 2019). "The expression of ANXA10 mRNA was further evaluated by RT-PCR in the Cul4A knockdown H460 and A549 lung cancer cells." (PMID 31052599, 2019). "Cul4a is abnormally expressed in various cancers, and many studies have shown that it is closely related to the proliferation and invasion of lung cancer, gastric cancer, and prostate cancer." (PMID 31178959, 2019). "Receiver operating characteristic (ROC) curves and the Youden index were used to determine the optimal cutoff value of Cul4A IRS for disease recurrence after surgical resection of NSCLC lung cancer." (PMID 31052599, 2019). "Tail vein injection models were established using H460 and A549 cells that were stably transfected with Cul4A shRNA to confirm the effect of Cul4A on lung cancer metastasis." (PMID 31052599, 2019). "In this study, we attempted to elucidate the potential role of Cul4A in growth and tumorigenesis of lung cancer cells." (PMID 26969027, 2016). "Further studies to elucidate the association of Cul4A with TGFBI and TIEG1 in lung cancer cells are ongoing in our laboratory." (PMID 26969027, 2016).